IL2 (interleukin 2)
Diseases named in the same sentence as IL2 in open-access papers (continued):
Sharing a sentence is not in itself a finding about the gene and the disease.
melanoma (continued). "In the current study, we investigated the combination of TBI pre-conditioning and IL-2 post-conditioning regarding the therapeutic effect and immunological profile in ACT of murine melanoma." (PMID 36497152, 2022). "In melanoma, the eosinophil count has been shown to positively correlate with survival and better response to immune checkpoint inhibition (ICI) or IL-2." (PMID 35565423, 2022). "It is also possible that IL-2, which we have shown is induced by CDDO-Me in T cell monocultures and in tri-cultures that include monocytes, T cells, and melanoma cells, contributes to T cell-mediated alterations in TAM activation." (PMID 35265066, 2022). "Here, by using an ACT model of murine melanoma, we evaluate the effect of the total body irradiation (TBI) and interleukin-2 (IL-2) treatment combination." (PMID 36497152, 2022). "After clinical trials, both IL-2 and IFN-α demonstrated only mild clinical benefit when used as monotherapy and are approved by the FDA for use in melanoma." (PMID 35495634, 2022). "Interleukin-2 (IL-2) is an important cytokine in survival, expansion, function of CD8+ T cells and natural killer cells in immunotherapy of melanoma and renal cell carcinomas." (PMID 35354847, 2022). "F42K, a mutant IL-2, induced a systematic decrease in the expansion of ICOS+ Treg cells, which promoted the expansion of NK cells and inhibited the tumor growth of melanoma more efficiently than wild-type IL-2." (PMID 35585567, 2022). "To investigate the therapeutic efficacy of the nanobody–IL-2 fusions, we employed the B16F10 melanoma model, previously shown to express EIIIB+FN by microscopy, immuno-PET/CT-imaging, and immunohistochemistry." (PMID 36712341, 2022). "The therapy, known as AIP, combines the Trp1-targeting antibody TA99 (A), extended half-life IL-2 (I), and an anti-PD-1 antibody (P), and results in cures in about half of mice with B16F10 melanoma." (PMID 35812387, 2022). "In a syngeneic melanoma model, the same EDA-targeting IL-2 immunocytokine increased the efficacy of both paclitaxel and dacarbazine." (PMID 33803078, 2021). "In a xenograft-harboring mouse model of CXCL10-transfected melanoma, overexpression of CXCR3 on NK cells after ex vivo growth with irradiated EBV-LCL feeder cells and IL-2 resulted in better trafficking and antitumor activity." (PMID 34970253, 2021). "A phase II trial incorporating anti-EDB IL-2 and TNF immunocytokines in 20 stage III and IV melanoma patients resulted in 30% of lesions experiencing a complete response." (PMID 33803078, 2021). "We obtained with our protocol numerous pure M1-CTLs which were producing high amounts of IFNγ, TNFα and IL-2, and were able to specifically lyse both MART-1-pulsed T2 cells and melanoma-derived cell lines very efficiently, with a high functional avidity." (PMID 34566953, 2021). "Cytokine therapy is the first immunotherapy used for cancer patients, with IFN-α and IL-2 approved by FDA as treatments for several malignant cancers, including lymphoma, hairy cell leukemia, melanoma and renal cell carcinoma." (PMID 35008589, 2021). "In B16 melanoma models, NK cells and CD8+ T cells synergistically clear tumors in response to anti-CTLA-4 and IL-2 treatment." (PMID 34376232, 2021). "NK cells from melanoma patients showed impaired activation of STAT1, a critical molecule in the IFNγ-mediated signaling pathway, after IL2 stimulation." (PMID 33809795, 2021). "Several studies highlighted NK cell ability to recognize and kill poorly differentiated tumors and that cytokine-activated (IL2 and/or IL15-activated) NK cells were effective against human breast, colon, melanoma and glioblastoma CSCs." (PMID 33806296, 2021). "Three days after the B16-F10 challenge, C57BL/6 mice sequentially received CTX, ex vivo-primed Pmel-1 cells (melanoma-specific T-cell receptor (TCR)-transgenic CD8+ T cells), and interleukin-2 (IL-2)." (PMID 34493727, 2021).
melanoma (continued). "Higher activation levels of IFN-γ and IL-2 in CD8+ T cells from TDLN and SP in CC and melanoma models were also found in the combination treatment group relative to those of the monotherapy groups." (PMID 33918641, 2021). "This beneficial effect was related to the attachment of IL-2 and anti-CD137 to the surface of liposomes that allowed a rapid accumulation of immunoliposomes in melanoma, thus, minimizing the systemic utilization, as well as the risk of toxicity." (PMID 33546290, 2021). "An example of TME modulation is the use of nanoscale liposomal polymeric gels to co-deliver a TGF-β inhibitor and IL-2 to the TME, resulting in decreased tumor growth and increased numbers of NK cells in the tumor of a B16 mouse melanoma model." (PMID 34572949, 2021). "Interleukin-2 (IL-2) antigen stimulates memory CD8(+) T cells production, and high relative IL-2 production in T cells of melanoma tend to perform memory CD8(+) T cells phenotype and superior proliferative capacity compared to cells with low IL-2 production." (PMID 34238310, 2021). "Another study found that EZH2 inactivation reversed the resistance to anti-CTLA-4 and IL-2 immunotherapy and suppressed melanoma growth in a consequence of accumulating IFN γ, producing PD-1 low CD8+ T cells and PD-L1 downregulation on melanoma cells." (PMID 32708698, 2020). "For example, Interleukin 2 (IL-2) is a kind of representative cytokines, which could regulate the survival, proliferation, and differentiation of T cell and natural killer (NK) cell, which could be put to use in the treatment of malignant melanoma and renal cell carcinoma." (PMID 33240857, 2020). "Until 2014, regimens for the treatment of advanced melanoma mainly comprised cytotoxic agents such as dacarbazine (DTIC) and cytokines (e.g., type I interferon (IFN), high-dose interleukin (IL)-2, etc.)." (PMID 32948031, 2020). "The objective of this study was to evaluate the feasibility, safety, and efficacy of combination high-dose IPI and high-dose IL-2 in patients with histologically confirmed advanced unresectable stage III and IV melanoma." (PMID 31998643, 2020). "Subsequently, in patients with advanced melanoma, pre-treatment serum VEGF and fibronectin have been shown to be inversely correlated with response to IL-2 treatment." (PMID 32610601, 2020). "Neo2/15 augmented the therapeutic efficacy of the melanoma-specific antibody TA99 in a preclinical model and had a lower toxicity profile compared with recombinant murine IL-2." (PMID 32019478, 2020). "Delay in tumor growth and survival prolongation were witnessed in melanoma with a combination of CTLA-4 blockade and IL-2 immunotherapy, indicating synergism." (PMID 32117298, 2020). "Patients assigned to IL-2 monotherapy who exhibited progression of melanoma after cycle 2 were allowed to crossover and receive SBRT and additional IL-2." (PMID 32467299, 2020). "High-dose IL-2 received FDA approval for metastatic renal cell cancer in 1992 and advanced melanoma in 1998." (PMID 33096755, 2020). "Soluble serum proteins as possible biomarkers were first suggested in studies of advanced melanoma and colorectal cancer (CRC) patients with high doses of IL-2." (PMID 32610601, 2020). "Peritumoral injection of nanoparticles loaded with potent immunostimulating agents as IL-2 has proved the efficacy to enhance the infiltration and activation of CD4+ and CD8+ T cells in melanoma models." (PMID 32225049, 2020). "Initially, immunotherapy was employed in melanoma treatment with administration of interferon and interleukin cytokines, such as IFN-α and IL-2, which were approved by the FDA with melanoma indications in 1996 and 1998, respectively." (PMID 33092131, 2020). "Treating melanoma patients with ex vivo expanded TIL and high dose IL-2 (720,000 IU/kg) led to complete remission in 20 of 93 patients and some patients experienced long-term remission." (PMID 30842774, 2019).
melanoma (continued). "To date, IL-2 and IFN-α are the only FDA-approved cytokines as adjuvant therapeutic agents for the treatment of melanoma, although other cytokines (IL-12, IL-15, IL-18, IL-21, and GM-CSF) have shown profound results in clinical settings." (PMID 31134073, 2019). "Due to the high immunogenicity of melanoma, presented by its historical response to interferon alpha (IFN-α) and interleukin 2 (Il-2), melanoma cells are able to induce a cytotoxic T cell-mediated immune response." (PMID 30871206, 2019). "Several ongoing investigator initiated trials are evaluating concurrent or rapid sequential use of HD IL-2 and anti-PD1 agents, in both melanoma and mRCC, and are evaluating immune parameters and biomarkers." (PMID 30917871, 2019). "Meanwhile, proliferation and CD69 expression of NK cells are increased in the context of IL-2, which is important for NK cells to reinforce the antitumor activity of BRAF inhibitor by perforin-dependent pathway in a BRAF-mutant melanoma mouse model." (PMID 31134073, 2019). "We have previously demonstrated that treatment with an anti-tumor antigen antibody and a fusion protein bestowing prolonged IL-2 signaling (i.e., Lip-MSA-IL-2 used here) led to significantly improved survival in a melanoma mouse model." (PMID 31114758, 2019). "Related to melanoma, an NDV vector based on the LaSota strain expressing IL-2 and IL-15 efficiently infected tumor cells and demonstrated superior tumor growth suppression compared to the recombinant NDV (rNDV) vector." (PMID 30832256, 2019). "IL-2 administration was approved in the 1990s for the treatment of metastatic RCC and melanoma patients." (PMID 32010130, 2019). "Cytokines such as interleukin (IL)-2, IL-12, IL-15, and interferon-α (INF-α) can promote the immune recognition of melanoma and thus have function of regulating immunity." (PMID 31998135, 2019). "Compared with wild-type IL-2, FSD13 greatly limited the growth, invasion into adjacent tissues, and metastasis of melanoma metastatic into the lung." (PMID 30250191, 2018). "Interleukin-2 (IL-2) is a cytokine immunotherapy approved by the FDA in 1992 that shows rare, but dramatic activity in metastatic renal cell carcinoma and melanoma." (PMID 30400822, 2018). "Ezh2 inactivation reversed this resistance and synergized with anti-CTLA-4 and IL-2 immunotherapy to lead to intratumorally accumulation of IFN-γ-producing PD-1low CD8+ T cells and PD-L1 downregulation to suppress melanoma growth." (PMID 29556394, 2018). "In co-culture experiments using F10-OVA melanoma cells and tumor-specific CD3+ T cells, EGCG reduced PD-L1 mRNA expression about 30% in F10-OVA cells and restored interleukin-2 mRNA expression in tumor-specific CD3+ T cells." (PMID 30126206, 2018). "In summary, Tα1-Fc inhibited the tumor growth on melanoma with an increased expression of IFN-γ, IL-2, and CD86 and of tumor-infiltrating CD4+ T and CD8+ T cells." (PMID 30120362, 2018). "On melanoma models, IFN-γ and IL-2 were upregulated by either Tα1 or Tα1-Fc in which the concentration of the two cytokines of the Tα1-Fc group showed a significant difference compared with that of the PBS group (p = 0.0016, p = 0.0032)." (PMID 30120362, 2018). "Both soluble and liposomal αCD137/IL-2-Fc induced intracellular pSTAT5 activation in CD8 T-cells and NK cells in both primary and lung metastatic melanoma models, with the soluble agents activating pSTAT5 in NK cells slightly more effectively than liposomes." (PMID 29295974, 2018). "All advanced melanoma patients treated with TILs using the same TIL expansion methodology and same treatment interleukin-2 (IL-2) regimen between 2009 and 2012 were included." (PMID 29750176, 2018). "At present, only 11 therapeutic choices against melanoma have been approved for clinical use, including BRAF and MEK inhibitors and therapeutic immune checkpoint inhibitors as well as IL-2 or Interferon alpha." (PMID 29371600, 2018).
melanoma (continued). "The IT delivery of IL-2 together with the checkpoint inhibitor anti-CTLA-4, delivered either systemically or locally, represents a promising approach in melanoma patients (NCT01480323, NCT01672450)." (PMID 30619273, 2018). "We next evaluated the therapeutic efficacy of IL-2/mAb, IL-2WTFc and IL-23XFc in the B16F10 melanoma model." (PMID 28497796, 2017). "The melanoma immunotherapies include the cytokine therapies consisting of IFN-α and IL-2 and inhibitors to CTLA-4 (ipilimumab) and PD-1 (nivolumab, lambrolizumab and pembrolizumab)." (PMID 28567163, 2017). "In vitro expansion is also similar when either high dose IL-2 (1000 IU/ml), IL-15, or a combination of the two is used for human CD8 αβ T cells specific for melanoma, influenza, Epstein-Barr virus, and cytomegalovirus." (PMID 28239463, 2017). "Advances in the treatment of melanoma have focused on overcoming tumor-induced immune suppression and were initially established in the adjuvant setting with the use of IFN-α and HDB IL-2 in the treatment of metastatic disease." (PMID 28434398, 2017). "Various groups have evaluated utility of predictive biomarkers to predict benefit to HD IL-2 in RCC and melanoma." (PMID 28923120, 2017). "Since the Food and Drug Administration’s (FDA) approval of HD IL2 for RCC in 1992 and for melanoma in 1998, it has been widely used in treatment of both malignancies." (PMID 26799322, 2016). "Utilization of HD IL2 for RCC and melanoma appears to be declining after 2005 and 2009 respectively." (PMID 26799322, 2016). "NK cells, cultured with IL-2, IL-15 or IL-15/IL-18 and in the presence of either BRAF-i or MEK-i, were analyzed for their ability to kill different melanoma cell lines including MeCoP, MeTA, MeDeBO and FO-1." (PMID 27563819, 2016). "For instance, in B16 murine melanoma, anti-TGF-β therapy in combination with interleukin-2 reduced the number of lung metastases." (PMID 27708249, 2016). "High dose bolus IL-2 is approved by the FDA to treat renal carcinoma and melanoma, while low dose IL-2 therapies are currently tested in patients suffering from chronic graft-versus host disease (GVHD) or diabetes." (PMID 26731275, 2016). "Co-injection of IL2-GMCSF and inactivated B16F10 mouse melanoma cells induced complete immunoprotective responses in about 30 % of mice." (PMID 26850448, 2016). "Treatment with high-dose IL-2 has been documented to induce a complete response in patients with metastatic renal cell carcinoma (RCC), and promote tumor regression in melanoma, but only a small percentage of patients respond." (PMID 27660705, 2016). "Preclinically, combination therapy with epacadostat and anti-CTLA-4 or anti-PD-1/PD-L1 improved tumor control and increased IL-2 production and CD8 T-cell proliferation in murine melanoma better than single agent therapy." (PMID 27192116, 2016). "Moreover, NK cells from melanoma metastatic lymph nodes were found surrounding tumor cell clusters and although they were mostly CD56bright and inactive, they could be activated ex vivo by IL-2 or IL-15 and could lyse metastatic melanoma cells more efficiently than blood-derived NK cells." (PMID 25674087, 2015). "Until recently, systemic chemotherapies (dacarbazine), hydroxyurea, or immunotherapy with high-dose interleukin-2 (IL-2) were the only treatment options approved by the U.S. Food and Drug Administration (FDA) for patients with advanced melanoma." (PMID 26305188, 2015). "Therefore, the purpose of this comprehensive review is to examine the use of IL-2 at different dosing regimens in metastatic renal cell carcinoma and melanoma to determine whether there is a target dose that produces optimal patient outcome with minimal toxicity." (PMID 26557408, 2015). "In summary, combination immunotherapy with high-dose IL-2 and CTLA-4 blockade, compared to either monotherapy alone, improves therapeutic responses in the poorly immunogenic B16 murine melanoma model." (PMID 25992289, 2015).
melanoma (continued). "In the interim, the data support clinical development of IL-2 and CTLA-4 blockade as a rational combination immunotherapy for patients with melanoma." (PMID 25992289, 2015). "In melanoma, which is considered among the most immunogenic of tumor types, ECT combined with IL-2 induced tumor cell death." (PMID 26155423, 2015). "Since secretion of IL-2 is pivotal to the lymphocyte proliferative response and IFN-γ plays a key role in T cell cytotoxicity, the influence of melanoma-derived PAEP on the proliferation and cytotoxicity of T cells was then examined." (PMID 25785839, 2015). "Immune therapy for melanoma focused on recombinant cytokines interferon alpha-2b (IFN α-2b) and interleukin-2 (IL-2)." (PMID 26060497, 2015). "As shown with melanoma, mRNA levels of IFN-γ, TNF-α, IL-2, IL-18, IL-10, and VEGF-A were significantly decreased in kCYC mice compared with WT mice in draining LNs on day 14 (p < 0.05, respectively)." (PMID 26098776, 2015). "High dose IL-2 and CTLA-4 blockade have demonstrated clinical success in the treatment of advanced melanoma although the exact mechanism of their anti-tumor activity is not completely defined." (PMID 25992289, 2015). "Here, B6 mice were challenged with poorly immunogenic B16 melanoma on day 0, and treated with CTLA-4 blocking antibody (100 μg/mouse) on days 3, 6, and 9, and IL-2 (100,000 units) twice daily on days 4–8, or both." (PMID 25992289, 2015). "The combination of chemotherapy with immune response modifiers such as interleukin 2 (IL-2) or interferon-α (IFN-α), referred to as chemo-immunotherapy, has shown promising anti-tumor activity to melanoma." (PMID 24465710, 2014). "We had treatment follow-up data for 399 patients (252 with melanoma and 147 with RCC) after completion of IL-2 and survival data for all patients." (PMID 24855563, 2014). "The patients with melanoma and RCC who had stable disease as their best response after IL-2 also had clinically significant survivals." (PMID 24855563, 2014). "We report on the clinical outcomes of 500 patients with melanoma and RCC treated with high-dose IL-2 at our cancer center." (PMID 24855563, 2014). "The response rate and survival of patients with melanoma and RCC with high-dose IL-2 monotherapy reported here is comparable or superior to that described in other studies." (PMID 24855563, 2014). "Ipilimumab triggered, via FcγReceptorIIIA (CD16), ex vivo NK cells as well as PBMC, IL-2 activated NK and γδT cells to ADCC of CTLA-4+ melanoma cells." (PMID 23634660, 2013). "In this study, we extensively monitored the behavior of Tregs in early-stage melanoma patients who received low-dose CTX and low-dose IL-2 in a phase II randomized trial." (PMID 23589107, 2013). "Here, we have compared the effects of IL-2, -15 and −21 cytokines on the expansion and activation of TIL from single-cell suspensions of non-small cell lung cancer, ovarian cancer and melanoma." (PMID 23402380, 2013). "The improved killing activity against melanoma cells of NK d21H correlated with highest expression levels of NKG2D and NKp30, as compared to NK cells incubated with IL-2 or NK cultures expanded with protocols K and L." (PMID 23483943, 2013). "CD8+ T cells obtained from IL-21 aAPC-expanded melanoma TIL cultures exhibited significantly higher cytotoxic activity compared with CD8+ T cells obtained from IL-15 and IL-2 aAPC expanded TIL." (PMID 23402380, 2013). "IL-2 was initially described as T-cell growth factor and as a consequence used in immunotherapy of RCC and melanoma." (PMID 23118856, 2012). "Serum cytokine levels (including IL-1α, IL-1β, IL-2, IL-6, IL-10, IL-12, TNF-α, IFN-γ and IFN-α) were lower in A375 melanoma bearing mice treated with G3139 + VRP + ACV + PAC.PBP + DNR + X rays than in controls treated with physiological saline." (PMID 22233801, 2012).